CCR4 (C-C motif chemokine receptor 4)
Diseases named in the same sentence as CCR4 in open-access papers (continued):
Sharing a sentence is not in itself a finding about the gene and the disease.
renal carcinoma (5 papers, 2019 to 2023). A carcinoma arising from the epithelium of the renal parenchyma or the renal pelvis. "Over expressed CCR4 appeared to be treated as a biomarker for immune checkpoint inhibitor therapeutic response in renal cancer patients." (PMID 37988195, 2023). "The anti-CCR4 antibody Affi-5 altered the phenotype of the myeloid cells towards antitumor and reduced the weight of cancer in renal carcinoma mice." (PMID 32422889, 2020). "In a preclinical model of renal cancer, Affi 5, a CCR4 blocking mAb, reduced tumor growth affecting the phenotype of myeloid cells and increasing the number of infiltrating NK cells." (PMID 30894861, 2019). "CCR4 is now considered a target for renal carcinoma patients." (PMID 30894861, 2019).
rheumatoid arthritis (5 papers, 2020 to 2021). A chronic, systemic autoimmune disorder characterized by inflammation in the synovial membranes and articular surfaces. "High levels of chemokine receptor CCR4 on Tregs in peripheral blood have been associated with the presence of active rheumatoid arthritis, with levels of CCR4 on Tregs positively correlating to disease severity." (PMID 34796183, 2021). "In rheumatoid arthritis, CCR4 plays a critical role in CD4+ T cell migration to the synovium contributing to joint inflammation." (PMID 32973504, 2020). "Thus, the RA group showed an increased percentage of CCR4+ Tregs and a higher production of IL-10 and TGF-β, which may indicate a compensatory activated state of Treg cells in rheumatoid arthritis that could be caused by physiological mechanisms or the medications applied for treatment." (PMID 33809452, 2021). "Th17/Th22 (CXCR3−CCR4+), Th17.1 (CXCR3+CCR4−), DP (CXCR3+CCR4+), and DN (CXCR3−CCR4−) CCR6+ memTh, cells sorted from PBMC of healthy donors or treatment-naïve early rheumatoid arthritis (RA) patients, were cocultured with SF from RA patients with or without anti-IL17A, anti-IFNγ, or 1,25(OH)2D3." (PMID 34082814, 2021).
vitiligo (5 papers, 2021 to 2025). Generalized well circumscribed patches of leukoderma that are generally distributed over symmetric body locations and is due to autoimmune destruction of melanocytes. "To investigate whether CCR4 is critical for depigmentation, we adoptively transferred CFP‐PMEL CD8+ T cells (WT) or CCR4‐deficient CFP‐PMEL CD8+ T cells (CCR4−/−) into KRT14‐Kitl*4XTG2Bjl (Krt14‐Kitl*) mice to induce vitiligo." (PMID 34077992, 2021). "CCR4 is also important in the pathogenesis of vitiligo, which is characterized by skin depigmentation." (PMID 36555280, 2022). "The CCL17/CCR4 axis is also important for the onset of vitiligo in mice, and CCR4 neutralization reversed depigmentation in animals." (PMID 36555280, 2022). "We initially examined CCL17 and CCR4 messenger RNA (mRNA) levels in skin samples from lesion area and its surrounding normal areas of 30 vitiligo patients." (PMID 34077992, 2021). "This article aims to identify the role of CC chemokine ligand 17 (CCL17)–CC chemokine receptor 4 (CCR4) axis in vitiligo and provide new possibilities for the clinical treatment of vitiligo." (PMID 34077992, 2021). "To test the efficacy of CCR4 blockade as a treatment of vitiligo, we administered CCR4 neutralizing antibody or isotype control antibody to vitiligo mice." (PMID 34077992, 2021). "Here, we reported that the elevated expression of CCL17 and CCR4 is essential for the progression of vitiligo utilizing a mouse model." (PMID 34077992, 2021). "In this paper, we examined the expression of CCL17 and CCR4 in the lesion area and its surrounding normal areas of vitiligo 30 patients." (PMID 34077992, 2021). "Our results indicate that neutralization of CCR4 reverses depigmentation in vitiligo mice." (PMID 34077992, 2021). "In conclusion, our results demonstrated the high expression of CCL17, CCR4 and the elevated activation of CD8+ T cells in skin lesions of vitiligo patients." (PMID 34077992, 2021). "CCL22 activates the migration and activity of Tregs in vitiligo, which has been shown to be decreased in vitiligo skin, whereas no changes were found for CCR4, CCR5, CCR8 and cutaneous lymphocyte antigen (CLA)." (PMID 39274437, 2024). "CCR4 and CCL17 were highly expressed in the skins of patients with vitiligo." (PMID 36555280, 2022). "Several studies demonstrate reduced levels of CCL5/CCR4, CCL22, CCL21, and CCR6 in vitiligo skin, which could explain the failure of circulating Tregs to localize to the skin, thus suggesting that the modulating expression of these chemokines may be potential therapeutic targets in vitiligo." (PMID 36675037, 2023).
atherosclerosis (4 papers, 2019 to 2025). A disease characterized by the build-up of fatty material and calcium deposition in the arterial wall resulting in partial or complete occlusion of the arterial lumen. "CCL17 is expressed mainly by a subset of myeloid dendritic cells and promotes atherosclerosis by mediating T-cell chemotactic activity through its receptor CCR4." (PMID 40535169, 2025). "The literature has little to say about CCR4 and atherosclerosis clinically, with only one brief report that described a positive correlation between CCR4 expressing CD4 T cells and Gensini score in a population of patients undergoing invasive angiography." (PMID 37927302, 2023). "Chemokine-receptor profiling in T1D group was marked by a positive association between CCR2+ monocytes and CCR4+ T lymphocytes with DBP, as well as between CCR2+ and CXCR3+ B lymphocytes with TG, linking endothelial inflammation, atherosclerosis and dyslipidemia." (PMID 39109081, 2024). "One previous study on atherosclerosis in mice may relate to CCR4‐expressing Tregs; it demonstrated that dendritic cell‐derived CCL17 drove atherosclerosis by restricting T regulatory cell homeostasis." (PMID 37927302, 2023). "In the current study, both CCR4 and CCR8 are upregulated in IS current smoker patients, which may suggest a role of current smoking in increasing stroke injury by promoting atherosclerosis and platelet aggregation." (PMID 31436916, 2019). "In the Treg context, CCR2, CCR4 and CCR6 have previously been shown to be up‐regulated in Tregs migrating to non‐lymphoid tissues or sites of inflammation, and this may be the primary basis of their increase in the atherosclerosis phenotype." (PMID 37927302, 2023).
breast tumor (4 papers, 2013 to 2023). "To demonstrate the association between CCR4 and FOXP3 expression in core breast tumor tissue, we created a correlation coefficient plot, which further indicates that CCR4 expression is highly correlated with FOXP3 expression in breast tissue taken from different cohorts." (PMID 35222362, 2022). "We ablated or overexpressed FOXP3 in Treg cells and grew them on a breast tumor organoid bed to replicate the ex vivo TME to better understand the role of FOXP3 in CCR4 transcriptional activation." (PMID 35222362, 2022). "In breast tumors, this chemokine attracts peripheral blood CCR4+ regulatory T cells, which are then selectively activated in lymphoid tumor infiltrates, thus preventing effector T cell activation, while sustaining immune escape, and ultimately tumor progression." (PMID 23441221, 2013). "Furthermore, based on the homing activity of Tregs to cancer, such as from the CCL22/CCR4 axis, SRC-3 KO Tregs can aggressively move into breast tumors." (PMID 37253006, 2023). "CCR4 is known to be down regulated on Tregs after their sensitization to CCL22 but other chemokine receptors, such as CCR6, which are expressed on these Tregs, which is interaction with CCL20 production by breast tumor cells." (PMID 24124553, 2013).
gastric tumor (4 papers, 2012 to 2024). "Our previous study also showed increased CCR4 expression on gastric tumor-associated Treg, accompanied by increased expression of CCR4 ligands." (PMID 22319577, 2012).
hematoma (4 papers, 2022 to 2025). A hematoma is a collection of blood from a vascular structure into an extravascular space. "Similarly, hemoglobin content, an indicator of hematoma size, was higher in the ipsilateral hemisphere of CCR4−/− mice, further suggesting that CCR4 deficiency exacerbates hematoma expansion following ICH." (PMID 39996481, 2025). "Conversely, CCR4 overexpression in CCR4overexpress mice at 72 h post‐ICH resulted in significantly reduced hematoma volume and improved neurological outcomes compared to sham controls." (PMID 39996481, 2025). "Future studies should use various inhibitors of the CCR4/ERK/AP1/SRA signaling pathway to explore their role in hematoma clearance and functional recovery." (PMID 39996481, 2025). "Our findings extend previous work by revealing that the CCL17/CCR4 axis enhances hematoma clearance through the ERK/AP1/SRA pathway‐mediated microglial polarization." (PMID 39996481, 2025). "The study identifies the critical role of the CCL17/CCR4 axis in microglial polarization and hematoma clearance following intracerebral hemorrhage." (PMID 39996481, 2025). "We have conducted additional experiments specifically comparing the hematoma sizes between rCCL17 + CCR4−/− + ICH group and WT + ICH + rCCL17 group." (PMID 39996481, 2025). "Specifically, we found that the CCR4−/− + ICH + rCCL17 group exhibited impaired hematoma resolution compared to the WT + ICH + rCCL17 group." (PMID 39996481, 2025). "This investigation extends our previous work on CCL17/CCR4‐mediated hematoma resolution and provides new insights into potential therapeutic strategies for ICH treatment." (PMID 39996481, 2025). "Brain sections showed significantly smaller hematoma volumes in rCCL17‐treated CCR4overexpress mice compared to CCR4−/− and vehicle‐treated groups at 72 h post‐ICH." (PMID 39996481, 2025). "This study investigates the role of the CCL17/CCR4 axis in regulating microglial polarization and hematoma clearance following intracerebral hemorrhage (ICH), with a focus on the downstream ERK/AP1/SRA signaling pathway." (PMID 39996481, 2025). "This study investigates how the CCL17/CCR4 signaling pathway modulates microglial phenotype transition and enhances hematoma resolution after ICH, building upon our earlier findings showing CCR4's involvement in neuroinflammatory responses." (PMID 39996481, 2025). "In conclusion, our findings suggest that the CCL17/CCR4 axis plays a pivotal role in microglial polarization and hematoma clearance after ICH, with potential therapeutic implications." (PMID 39996481, 2025). "CCL17 therapy promotes early hematoma regression after intracerebral hemorrhage through the CCR4/ERK/Nrf2/CD163 pathway." (PMID 35959472, 2022). "Hematoma volume at 72 h post‐ICH was significantly larger in CCR4−/− mice compared to WT controls." (PMID 39996481, 2025). "It has been reported that treatment with CCL17, a specific ligand of CCR4, promotes hematoma resolution through the CCR4/ERK/Nrf2/CD163 pathway, thereby, improving neurological function, which is associated with microglia-mediated erythrocyte phagocytosis and clearance of tissue debris." (PMID 35959472, 2022). "However, the specific mechanisms by which the CCL17/CCR4 axis regulates microglial polarization and hematoma clearance remain unclear." (PMID 39996481, 2025). "In addition to the effects of CCL17 on hematoma resolution, the axis also could alleviate neuroinflammation and neuronal apoptosis via the CCR4/PI3K/AKT/Foxo1 signaling pathway at 72 h post-ICH." (PMID 36704330, 2022). "Using CRISPR‐mediated CCR4 disruption and CCR4 overexpression approaches in a mouse ICH model, we examined neurological outcomes, inflammatory responses, and hematoma volumes." (PMID 39996481, 2025). "Based on our preliminary data and published findings, we hypothesize that CCL17/CCR4 signaling modulates the ERK/AP1/SRA pathway to promote M2 polarization, thereby facilitating hematoma clearance and reducing secondary brain injury." (PMID 39996481, 2025).
hematoma (continued). "It was further identified that CD163 was responsible for the improved hematoma resolution effect by CCL17, which included activation of the C-C chemokine receptor 4 (CCR4) with downstream ERK and Nrf2 activation, improving the outcome of intracerebral hemorrhage in a relevant animal model." (PMID 39451197, 2024).
HIV-1 infection (4 papers, 2011 to 2024). The type species of lentivirus and the etiologic agent of acquired immunodeficiency syndrome (AIDS). "It has been shown that CCR6+CCR4+, CCR6+CXCR3+ and CCR6+CD90+ Th17 cell subsets are highly permissive to HIV-1 infection." (PMID 28509877, 2017). "Furthermore, as a result of differentiation, expression of other common cellular ligands essential for HIV-1 infection, such as CXCR4, CCR4, and CCR5, distinctly increased." (PMID 21226936, 2011).
Immunodeficiency (4 papers, 2009 to 2025). Failure of the immune system to protect the body adequately from infection, due to the absence or insufficiency of some component process or substance. "Collectively, our data reveal that CCR4 blockade is effective in the overall recovery of various levels of immune dysfunction in HBsAg-specific T cells including both CD4 and CD8 T cells that might help in HBV clearance." (PMID 37081509, 2023). "The up-regulations of CCR4 and IGLL1 serve as indicators of immunity disorders in KBD patients." (PMID 22235245, 2012).
lung adenocarcinoma (4 papers, 2021 to 2024). A carcinoma that arises from the lung and is characterized by the presence of malignant glandular epithelial cells. "The specific lysis of CCR4-positive cells in the lower chamber of treatment group A (100 ng/ml CCL17) on HLA-A2-positive lung adenocarcinoma H1993 cells was significantly stronger than that of treatment group B (without CCL17), and the difference was significant (p < 0.05)." (PMID 35321241, 2022).
metastatic disease (4 papers, 2011 to 2024). "Specifically, CXCR6, CCR2, CCR4, IL2Ra were both deleted and had lower gene expression in the primary versus metastatic tumors." (PMID 22194851, 2011). "Given that the CCR4-NOT complex is a non-specific enzyme, we focused on NANOS1, PUM2 and CPSF4, sequence-specific RNA binding proteins (RNABPs) that were identified in a CCR4-NOT-associated transcriptional network, to gain a better understanding of its role in metastatic disease." (PMID 38410477, 2024). "The integrated genetics and gene expression analysis that initially identified Cnot2 also implicated other genes associated with RNA deadenylation (Cnot8, Angel2, Tob1) as potential modulators of metastatic disease, suggesting that this function of CCR4-NOT might be a critical determinant." (PMID 26807845, 2016). "Importantly, due to the multifunctional nature of the CCR4-NOT complex, the ability of Cnot7 to promote metastatic disease was dependent on deadenylase activity." (PMID 26807845, 2016).
non-Hodgkin lymphoma (4 papers, 2014 to 2023). Distinct from Hodgkin lymphoma both morphologically and biologically, non-Hodgkin lymphoma (NHL) is characterized by the absence of Reed-Sternberg cells, can occur at any age, and usually presents as a localized or generalized lymphadenopathy associated with fever and weight loss. "A current trial testing CAR-T cells co-transduced with the chemokine receptor CCR4 is currently underway for patients with CD30+ non-Hodgkin’s lymphoma (NHL) but more clinical studies are needed to further investigate the therapeutic advantages of chemokine-receptor-expressing CAR-T cells." (PMID 32244520, 2020).
pneumonia (4 papers, 2020 to 2022). An acute, acute and chronic, or chronic inflammation focally or diffusely affecting the lung parenchyma, caused by an infection in one or both of the lungs (by bacteria, viruses, fungi, or mycoplasma.). "Trafficking of ILC3s to the lung during pneumonia was attributed to CCR4 expression, as deficiency of CCR4 in adoptively transferred ILC3s abrogated homing to the lungs in newborn mice." (PMID 33968082, 2021). "Commensal bacteria in the intestines of newborn mice were also found to induce expression of CCR4 on ILC3s, enabling subsequent migration to the lungs during pneumonia." (PMID 33968082, 2021). "Some studies have reported that hyperactivation of CCR4+ CCR6+ Th17 and high cytotoxicity of CD8+ T lymphocytes existed in patients with pneumonia." (PMID 32669467, 2020). "Increased transcription of chemokine receptors CCR2 (CCL2/monocyte chemoattractant protein-1 (MCP-1) receptor) and CCR5 (CCL3/MIP-1A receptor) were observed, indicating that these inflammatory signals were activated, but receptors XCR1, CCR4, and ACKR3 were downregulated in the pneumonia group." (PMID 36119044, 2022).
Stroke (4 papers, 2019 to 2024). Sudden impairment of blood flow to a part of the brain due to occlusion or rupture of an artery to the brain. "The intersection of the top 10 genes from the two stroke outcomes are seven genes with T2DM, these include CCR4, IFNA2, IL-9, IL-7, IL-5, CCR3, and IL-27." (PMID 32010048, 2019). "The seven important predictor genes (CCR4, IFNA2, IL-9, IL-7, IL-5, CCR3, and IL-27) that overlapped both stroke outcomes had mean fold change ranging from 3.98 to 35.06." (PMID 32010048, 2019). "IMM-H004 is a compound screened from a system of C27 (CKLF1 agonist peptide) and CCR4, and our previous studies have shown that CKLF1 may play an important and detrimental role in the early phase of a stroke." (PMID 30987181, 2019).
T-cell neoplasms (4 papers, 2015 to 2022). "Targeted therapies, such as antiCD30 immunotoxin brentuximab vedotin, antiCD38 antibody daratumumab, and anti-CCR4 antibody mogamulizumab are effective only in subsets of patients with T-cell neoplasms." (PMID 35600381, 2022). "The GATA-3 target genes shared across the continuum of T-cell neoplasms are therapeutically relevant, including immunomodulatory drugs (IMiDs) that lead to IKZF3 degradation, and the CCR4 specific monoclonal antibody mogamulizumab." (PMID 36329027, 2022).
tuberculosis (4 papers, 2011 to 2018). A chronic, recurrent infection caused by the bacterium Mycobacterium tuberculosis. "Our findings suggest that CD4+Foxp3+ cells play a time-dependent role in tuberculosis and highlight that CCR4 plays a critical role in the balance of IFN-γ-mediated inflammation by regulating the influx and function of CD4+Foxp3+ cells." (PMID 30584243, 2018). "Our findings are translationally relevant, as CD4+Foxp3+ cells or CCR4 could be a target for immunotherapy, considering the heterogeneity of tuberculosis in immunocompetent adults." (PMID 30584243, 2018). "The presence of a small, but significant, increased number of CCR4+ cells in our PLTB patients is in keeping with previous data The up-regulation of CCR4 expression in the lungs in an animal model of tuberculosis suggests the possibility of a Th2 response existing in PLTB." (PMID 21829471, 2011). "The percentage of CD27− and/or CCR4+ surface homing markers was studied on active TB and LTBI within the IFN-γ+CD4+ T-cells subset after M. tuberculosis specific stimulation." (PMID 30687314, 2018). "In summary, our findings on surface homing markers such as CD27 and CCR4 on M. tuberculosis specific CD4+ T-cells gather the required features for using them as potential TB biomarkers." (PMID 30687314, 2018).